HOTAIR (HOX transcript antisense RNA)
Diseases named in the same sentence as HOTAIR in open-access papers (continued):
Sharing a sentence is not in itself a finding about the gene and the disease.
cancer (continued). "Based on these data, we concluded that CAFs promoted metastasis by activating HOTAIR expression in cancer cells." (PMID 29325547, 2018). "Mounting evidence has revealed that HOTAIR, as a key epigenetic regulator, plays a pivotal role in initiation and progression of human malignant tumors, like esophageal squamous cell carcinoma, colorectal cancer and pancreatic cancer." (PMID 29416703, 2018). "As its expression can be used to predict the metastatic progression and overall survival, HOTAIR was proposed as a prognostic biomarker in different types of cancers." (PMID 30154386, 2018). "For example, increased expression of the lncRNA HOTAIR has been observed in primary breast tumors as well as metastases and, conversely, a decrease in its expression has been shown to prevent cancer invasiveness." (PMID 30619763, 2018). "HOTAIR, a long non-coding RNA overexpressed in most human cancers including OSCCs activates PI3K/Akt signalling by inactivating the tumor suppressor PTEN, an inhibitor of PI3K56." (PMID 30352996, 2018). "In conclusion, we have performed that HOTAIR exerts its effects on migration and invasion of cancer cells, at least in part, through the regulation of MKL1 expression via inhibition of miR206 expression." (PMID 29391067, 2018). "Many malignant tumor experiments have demonstrated that HOTAIR altered histone H3 lysine 27 methylation by recruiting PRC2 to suppress target genes and control Wnt/β-catenin." (PMID 29707567, 2018). "Together, these data suggest that HOTAIR exerts its effects on migration and invasion of cancer cells, at least in part, through the regulation of MKL1 via inhibition of miR206 expression in HeLa cells." (PMID 29391067, 2018). "Several researches have showed that the increased expression of 6 lncRNAs (H19, UCA1, TUG1, MALAT1, SPRY4-IT1, and HOTAIR) was correlated to poor prognostic outcome of cancers, those findings in consist with our results." (PMID 29870555, 2018). "Here, we summarize the emerging findings for three well-known oncogenic lncRNAs (namely, ANRIL, H19, and HOTAIR) and discuss their potential roles in obesity-induced cancers." (PMID 30154386, 2018). "Together, these findings suggest that MKL1 is an important player in the functions of HOTAIR in the migration and invasion of cancer cells." (PMID 29391067, 2018). "HOTAIR is a relatively well-studied oncogene, its expression level in cancer is an efficient predictor of metastasis and survival." (PMID 30598113, 2018). "Later, researchers found that HOTAIR is upregulated in different kinds of cancers and promotes cancer metastasis through by regulating the localization of PRC2." (PMID 29416704, 2018). "As HIF-1α was reported to upregulate the expression of HOTAIR at transcriptional level in hypoxic cancer cells, we examined the effect of HIF-1α overexpression on the level of HOTAIR in HeLa and C33A cells." (PMID 30355300, 2018). "HOTAIR is also related to metastasis and progression of other cancers, such as liver cancer, lung cancer, colorectal cancer, gastric cancer, and so on." (PMID 30459803, 2018). "Based on our data, we propose a model depicting the molecular mechanism of HOTAIR in regulating migration and invasion of cancer cells." (PMID 29391067, 2018). "As a novel regulator in tumorigenesis, the expression of HOTAIR negatively correlates with tumor progression in several cancers, such as breast cancer, pancreatic cancer, colorectal cancer, gastric cancer and hepatocellular carcinoma." (PMID 29391067, 2018). "In summary, this work reveals HOXA9 as a novel direct regulator of HOTAIR, and establishes HOTAIR as an independent prognostic marker, providing new therapeutic opportunities to treat this highly aggressive cancer." (PMID 29644006, 2018). "HOTAIR depletion can lead to cancer cell apoptosis in vitro, and decelerate tumor growth via activating mitochondrial-related cell death pathway in HNSCC both in vitro and in vivo." (PMID 29416703, 2018).
cancer (continued). "Meanwhile, HOTAIR is a tumorigenic factor and can be adopted as a diagnosis or predictive biomarker in various cancer types, those findings in consist with our results." (PMID 28977961, 2017). "Increasing evidence suggests that the lncRNA HOTAIR acts as an oncogene, promoting the development and progression of various types of cancer." (PMID 28938586, 2017). "For example, HOTAIR reprograms chromatin state to promote cancer metastasis by redirecting the Polycomb Repressive Complex 2 (PRC2) to active genes involved in embryogenesis while suppressing a set of genes that block metastases." (PMID 28423633, 2017). "Several miRNAs regulate the expression of HOTAIR and HOTAIR interacts with many miRNAs to support cancer transformation." (PMID 29469819, 2017). "The oncogene functions and unfavorable prognostic significance of HOTAIR have been reported in multiple cancers including BC, whereas the expression and functions of other HOX-associated lncRNAs in cancer cell lines have not been extensively studied." (PMID 28036281, 2017). "The up-regulation of the HOTAIR expression was related to poor prognostic outcome of different cancers, those findings in consist with our results." (PMID 28118613, 2017). "Previous meta-analyses have demonstrated higher expression of HOTAIR to correlate with poor prognosis in patients with cervical, ovarian, esophageal and gastric cancer." (PMID 29069846, 2017). "Significant inhibition of KYSE30 cell growth was observed after depletion of HOTAIR expression after 96 h, indicating that HOTAIR plays an essential role in the control of cancer cell growth." (PMID 29156804, 2017). "As cancer stem cells (CSCs) are responsible for maintaining tumor cells population and play a major role in cancer metastasis, reinitiating, therapeutic resistance and transplantation, it is justified to look for a possible role of HOTAIR in breast CSCs." (PMID 29469819, 2017). "HOTAIR upregulation was also observed in several other cancer types where numerous regulatory factors control its expression, including TGF-β." (PMID 28671581, 2017). "Because PTEN acts as a tumor repressor by inhibiting the phosphatidylinositol 3-kinase (PI3K) signaling pathway, the increased expression of HOTAIR in LSCC promotes cancer progression by activating the PI3K pathway." (PMID 27802187, 2017). "The lncRNAs such as MALAT1, GAS5, ANRIL, PVT1, CCAT2 and HOTAIR etc. were found to be novel promising biomarkers to predict a poor prognosis in human cancers." (PMID 28594897, 2017). "A total of 3207 patients from 32 studies were included to explore the prognostic value of HOTAIR expression in human cancers." (PMID 28591050, 2017). "HOTAIR is another lncRNA that plays a role in the development of multiple types of cancer by interacting with Polycomb Repressive Complex 2 (PRC2)." (PMID 28164117, 2017). "As a well-known lncRNA, HOTAIR is found to function as a modular scaffold for histone modification proteins, thus targeting special genes and promoting the metastasis of cancer." (PMID 29299179, 2017). "Therefore, the interaction of HOTAIR with MMPs may partly underline its role in cancer progression." (PMID 29469819, 2017). "The most important role of HOTAIR can be attributed to cancer progression as its overexpression stimulates invasion and metastasis." (PMID 29469819, 2017). "We performed a meta-analysis to summarize the results of common lncRNAs (HOTAIR, PRNCR1, POLR2E and H19) polymorphisms on cancer risk, by using the random-effect model to obtain the odds ratio (ORs) and 95% confidence interval (95%CI)." (PMID 28159929, 2017). "Subgroup analysis uncovered a relationship between high HOTAIR expression and poor prognosis in all cancer types studied." (PMID 28591050, 2017). "The data showed that the HOTAIR is significantly up-regulated in cancer cell lines and tumor tissues compared to normal breast samples." (PMID 29209357, 2017).
cancer (continued). "HOTAIR enhances cancer progression and malignancy by leading to altered H3K27 methylation due to retargeting of PRC2." (PMID 28811863, 2017). "HOTAIR is overexpressed in breast, colon and liver cancers, and plays important roles in cancer invasion and metastasis." (PMID 28177890, 2017). "HOTAIR accumulation in cancer cells induces the hypermethylation of CpG islands in the PTEN gene, reducing the expression of PTEN at the mRNA and protein levels." (PMID 27802187, 2017). "Circulating noncoding RNAs such as miR-21, MALAT-1, HOTAIR have been used as biomarkers for cancer diagnosis." (PMID 29137379, 2017). "Our meta-analysis results revealed that these four lncRNAs polymorphisms (HOTAIR rs920778, PRNCR1 rs1016343 and rs16901946, POLR2E rs3787016) can contribute to cancer risk." (PMID 28159929, 2017). "Functional studies of the lncRNA HOTAIR (HOX transcript antisense RNA) provide compelling evidence for therapeutic targeting of HOTAIR in cancer, but targeting lncRNAs in vivo has proven to be difficult." (PMID 28420874, 2017). "Therefore, HOTAIR can be involved in estrogen signaling and in consequence in estrogen-dependent cancer transformation, although the causative relationship between HOTAIR and such cancers cannot be established on the basis of the presence of EREs, as these motifs are common in the human genes." (PMID 29469819, 2017). "Clinical studies demonstrated that HOTAIR overexpression is a predictor of tumor progression and overall survival in patients with diverse types of cancer." (PMID 28938586, 2017). "In conclusion, our meta-analysis showed that lncRNA HOTAIR rs920778, PRNCR1 rs1016343 and rs16901946, POLR2E rs3787016 were associated with cancer susceptibility." (PMID 28159929, 2017). "The up-regulation of several other lncRNAs, such as HOTAIR and MVIH, and the downregulation of H19 have been associated with poor prognosis in cancers." (PMID 28346506, 2017). "HOTAIR has been reported to exert pro-oncogenic functions in many cancers, including PC and is significantly overexpressed in PC tissues, with HOTAIR knockdown impairing cell growth, blocking cell cycle progression, and inducing apoptosis in PC cells." (PMID 29137412, 2017). "HOTAIR is an oncogenic factor and has been used as a prognostic biomarker in different cancer types." (PMID 29156779, 2017). "As the first lincRNA identified to regulate genes at a distance, HOTAIR is overexpressed in lots of cancers, such as breast, gastric, lung, esophageal and liver cancer." (PMID 29222472, 2017). "We demonstrated that overexpression of HOTAIR in OCSC enhanced cancer stemness and metastasis, whereas down-regulation of HOTAIR expression markedly attenuated the oncogenicity and invasiveness as well as tumor growth in xenograft nude mice." (PMID 29228709, 2017). "As an oncogenic lncRNA, HOTAIR is involved in epigenetic gene silencing, cell growth, and progression of various cancers." (PMID 29138748, 2017). "Chemotherapy is a common clinical therapy for cancers, and many studies have reported that HOTAIR plays a crucial role in drug resistance." (PMID 28591050, 2017). "For example, knockdown of HOTAIR or MALAT1 with siRNAs inhibits cancer-cell proliferation and increases apoptosis." (PMID 27802187, 2017). "One of the first reported and characterized lncRNA involved in cancer progression through genome-wide epigenetic reprogramming was HOTAIR." (PMID 28634418, 2017). "The aberrant expression of HOTAIR has been reported in a variety of human cancers such as breast cancer, gastric cancer, colorectal cancer and liver cancer." (PMID 28938673, 2017). "Upregulation of HOTAIR was shown to be a marker of poor prognosis in a number of cancers, including HCC." (PMID 28810927, 2017). "Recently, a relationship between the expression of particular lncRNAs and the survival of cancer patients has also been increasingly reported, especially HOTAIR, a highly oncogenic lncRNA in numerous human malignancies." (PMID 29108287, 2017).
cancer (continued). "HOTAIR is up-regulated in many types of cancer and is related to oncogenesis, metastasis and poor prognosis in HNC, cervical cancer, and colon cancer." (PMID 27802187, 2017). "HOTAIR also increases cancer invasiveness and metastasis by inducing PRC2 retargeting and affecting the methylation of H3 K27." (PMID 28649178, 2017). "Given that its overexpression is observed in numerous human malignant tumors, HOTAIR offers a hopeful approach for anti-cancer treatment." (PMID 29299179, 2017). "In this regard, HOX antisense intergenic RNA “HOTAIR” is frequently overexpressed, promotes metastasis and is predictive of decreased survival in a range of cancers and leads to homeotic transformation." (PMID 28420874, 2017). "As a well-known long non-coding RNA, HOTAIR has been demonstrated to be involved in carcinogenesis and progression of various human cancers." (PMID 28938673, 2017). "HOTAIR is a well-known molecule in the lncRNA world due to its involvement in reprogramming chromatin organization and promoting cancer cell metastasis." (PMID 29156804, 2017). "HOTAIR was the first lncRNA found to be involved in tumor and has been proven to be raised in a variety of human cancers." (PMID 28977961, 2017). "Consistent with our results, a number of studies have demonstrated that HOTAIR expression is related to clinical parameters and the prognosis of cancer patients." (PMID 29108287, 2017). "The overexpression of HOTAIR in various cancer types has led to its examination as a candidate molecule for the diagnosis and treatment of the disease." (PMID 27246974, 2016). "In a cancer setting, HOTAIR recruits PRC2 subunits in promoter regions of tumor suppressor genes, which leads to their transcriptional repression and favours tumor progression." (PMID 27340923, 2016). "An example, HOTAIR, overexpressed in multiple cancer types because of effects of c-Myc, TGF-β or other regulatory factors." (PMID 27147563, 2016). "HOTAIR, a typical trans-acting lncRNA, is highly expressed in a variety of cancers and thus have emerged as a potential anticancer target." (PMID 26962687, 2016). "HOTAIR is the first discovered tumor related lncRNA and is upregulated in breast, hepatocellular, colorectal, pancreatic, and other cancers in recent years." (PMID 27660759, 2016). "The expression level of genes related to cancer progression was regulated by HOTAIR via interacting with PCR2 complex." (PMID 27751178, 2016). "In PC, HOTAIR was up-regulated and functioned as an “onco-lncRNA” to promote cell proliferation, regulate cell cycle progression, and inhibit cancer cell apoptosis." (PMID 27429196, 2016). "Further studies are warranted to advance our understanding of the involvement of HOTAIR in cancer development, since this lncRNA is a potential target for cancer prevention and treatment." (PMID 27148353, 2016). "Some well-known cancer-associated lncRNAs, such as H19, XIST, HOTAIR, MALAT1, MEG3, HNF1A-AS1 and PVT1, have indicated oncogenic and/or tumor suppressive roles like protein-coding genes in various cancers." (PMID 27074572, 2016). "In a ChIRP dataset of HOTAIR in cancer, there was a trend in which HOTAIR-mediated targets slightly overlapped with interacting genes (p = 0.09, hypergeometric test)." (PMID 26943771, 2016). "Here, we report that microRNA miR-125a-5p decreases and releases caspase 2 to promote cancer cell apoptosis after HOTAIR knockdown." (PMID 26962687, 2016). "Collectively, as is the case with other cancers, HOTAIR facilitates cell proliferation, regulates cell cycle and inhibits cell apoptosis through PRC2 and GDF15 mRNA in PC." (PMID 27429196, 2016). "Among the well documented lncRNAs involved in cancer migration and metastasis are HOTAIR and MALAT1." (PMID 26871474, 2016). "To date, the relationship between the aberrant expression of HOTAIR and cancer prognosis has been explored by many researchers." (PMID 27010768, 2016).
cancer (continued). "The importance of HOTAIR in cancer biology has sparked interest in using HOTAIR as a biomarker and potential therapeutic target." (PMID 26800519, 2016). "Given the importance of HOTAIR in tumor progression, there is increased interest in using HOTAIR as a biomarker as well as a therapeutic target in cancers in which HOTAIR is aberrantly expressed." (PMID 26800519, 2016). "Loss of HOTAIR, a lncRNA in the mammalian HOXC locus that binds to and targets the PRC2 complex to the HOXD locus, can inhibit cancer invasiveness, particularly in cells that possess excessive PRC2 activity." (PMID 26967389, 2016). "The HOTAIR serum level was also greater in cancer patients (4.20794 ± 0.89) compared with control patients (0.76813 ± 0.24)." (PMID 27323817, 2016). "Increasing evidence suggests that HOTAIR has an important role in cell growth, invasion, cancer metastasis, EMT, and stemness." (PMID 27323817, 2016). "The expression level of HOTAIR was markedly up regulated in many cancers, which play an important role in multiple biological progress of tumor development." (PMID 27751178, 2016). "We applied siRNAs targeting HOTAIR to various cancer cells, and observed apoptosis in all of these cell lines." (PMID 26962687, 2016). "Multiple lines of evidence have established that HOTAIR was involved in a large range of biological processes and diseases, particularly in cancer development and metastasis." (PMID 27686732, 2016). "HOTAIR (homeobox transcript antisense RNA), one of the prototypical long non-coding RNAs, has been verified overexpressed in multiple carcinomas and has emerged as a promising novel anticancer target." (PMID 26962687, 2016). "HOTAIR has been proposed as a putative biomarker for metastasis of human malignant tumors, and it is a powerful predictor of eventual metastasis and death." (PMID 26448942, 2015). "This was suggestive of a probable functional impairment of HOTAIR in PRC2-complex recruitment and subsequent loss of gene silencing marks, causing up-regulation of a variety of cancer related pathways." (PMID 26152361, 2015). "Extensive functional studies have indicated that overexpression of HOTAIR occurs in the majority of human solid tumors; strongly suggesting that HOTAIR promotes cancer progression." (PMID 25823657, 2015). "Our functional studies and the comparison of our expression data sets with those from other cancer cell types, which revealed minimal overlaps, indicate that effects of HOTAIR are strongly tissue-dependent and can even differ within one cancer type." (PMID 25994132, 2015). "A recent systematic review of 19 papers (including a total of 2255 patients) demonstrates consistently that HOTAIR expression is a poor prognostic marker across a large set of cancers." (PMID 26497652, 2015). "High expression levels of HOTAIR have been proven to correlate with metastasis and poor prognosis in many types of cancer." (PMID 26457124, 2015). "Overexpression of HOTAIR in breast, gastric and lung cancer cell lines, stimulates an increased invasive capacity in vitro." (PMID 26516918, 2015). "It was recently reported that the expression of HOTAIR is increased in various cancer entities and that high levels of expression correlate with cancer invasiveness, metastases and poor prognosis." (PMID 26497652, 2015). "A type of phosphoglycoprotein called osteopontin (OPN), which is an extracellular matrix protein, can transcriptionally activate and increase HOTAIR expression in cancer cells." (PMID 25859406, 2015). "In most of these reports, 70–80% of the cancer samples harbour low HOTAIR expression, while 20–30% of the cancer samples show high HOTAIR expression." (PMID 26152361, 2015).